CLDN3 (claudin 3)
Diseases named in the same sentence as CLDN3 in open-access papers (continued):
Sharing a sentence is not in itself a finding about the gene and the disease.
ovarian serous carcinoma (1 paper, 2009). "A well known marker of ovarian serous carcinoma, CLDN3, appeared at the top of the list." (PMID 19426511, 2009).
papillary breast carcinomas (1 paper, 2005). "CLDN3 positivity was observed in the majority (49/56) of cases examined (12 fibrocystic breasts, 5 DCIS, 23 IDC, 4 ILC, 2 mucinous, 2 tubular and 1 papillary breast carcinomas) and in all cases analyzed by confocal microscopy." (PMID 15743508, 2005).
poisoning (1 paper, 2008). A condition or physical state produced by the ingestion, injection, inhalation of or exposure to a deleterious agent. "Both claudin-4 and claudin-3 (to a lesser extent) function as receptors for Clostridium perfringens enterotoxin (CPE), the virulence factor responsible for the symptoms of C. perfringens strain A food poisoning." (PMID 18648369, 2008).
polyp (1 paper, 2025). A usually exophytic mass attached to the underlying tissue by a broad base or a thin stalk. "Animal experiments showed that claudin-3 expression was reduced by 50% within 5 mm of polyp margins, but serum DAO remained normal, consistent with the present findings." (PMID 40520790, 2025).
serous ovarian tumors (1 paper, 2025). "Most striking is CLDN3: TCGA data demonstrate that CLDN3 mRNA levels are higher than CLDN4 or CLDN1 in serous ovarian tumors." (PMID 40687428, 2025).
squamous non-small cell lung carcinoma (1 paper, 2023). "Furthermore, CLDN3 was uncovered as a positive regulator of cancer stemness in non-squamous non-small cell lung carcinoma, where stemness suppression and chemoresistance reversal were observed upon CLDN3 transcriptional activity downregulation." (PMID 36672179, 2023).
ulcers (1 paper, 2021). "Furthermore, intestinal surface epithelium in a vicinity of mucosal erosions and ulcers, in addition to decreased membranous claudin-3 expression, showed internalization of claudin-3 and claudin-8 into the cell cytoplasm." (PMID 34867313, 2021).
vasculitis (1 paper, 2023). "Moreover, recent experimental data demonstrated defective intestinal barrier with decreased expression of tight junction proteins such as Occludin, Claudin-3, and ZO-1 in LCWE-induced KD vasculitis model, and IVIG treatment could improve gut leakage to alleviate cardiovascular injuries." (PMID 37398673, 2023).
viral infection (1 paper, 2014). "For example, over half of these genes have been previously associated with viral infection or replication, or have been found to physically interact with viral proteins (e.g. CLDN3; CRHR2; ILF2; ILF3; LTF; miR-122; RCHY1; and, RUVBL2)." (PMID 25079789, 2014).
Williams syndrome (1 paper, 2025). "CLDN3 is a single exon gene spanning 1274 bases in total at 7q11.23, within the critical region deleted in Williams syndrome, a developmental disorder characterized by learning difficulties, distinctive facial features, and cardiovascular problems." (PMID 41442065, 2025).
tumor (108 papers, 2005 to 2026). "The striking associations between a reduced CLDN3 expression and unfavorable histopathological tumor parameters and poor prognosis in ccRCC represents a key finding of our study." (PMID 39658782, 2024). "Because both downregulation and upregulation of CLDN3 have been found in different tumor entities and both alterations have been associated with aggressive tumor characteristics, a tissue type dependency of CLDN3 function has been assumed." (PMID 39658782, 2024). "This suggests that the low-risk group, in the early stages of tumor development, is more suitable for targeted treatment of CLDN3." (PMID 38534739, 2024). "Increased claudin-3 protein expression is associated with poor staging, grading, and pattern of tumor growth." (PMID 38188015, 2023). "The compensational effects of other junction proteins upon claudin-3 deficiency in our tumor model need further study." (PMID 36261482, 2022). "CLDN3 showed association with tumor grade (grade 1 and 2 tumors were grouped together, while grade 3 tumors were in a separate group): higher CLDN3 levels were found in high grade tumors (p = 0.0005)." (PMID 34531452, 2021). "Although CLDN3 is known to function as a tumor suppressor in certain cancers, we found that a high CLDN3 expression was associated with poor RFS, OS, DMFS, and PPS in all patients." (PMID 33714203, 2021). "In fact, the selectivity of CPE tumor cell eradication was further supported by the use of the isogenic Sk-Mel5 cells, in which only the claudin-3 expressing cells were susceptible towards CPE action and claudin negative cells remained unaffected." (PMID 28193196, 2017). "In fact, both CD9 and claudin-3 proteins are present in TEMM on tumor cells and have been strongly linked to cancer malignancy." (PMID 25356755, 2014). "CLDN3 is an essential cytoskeletal protein in tight junctions, and it is currently widely believed that the loss of intercellular adhesion can lead to the destruction of tight junctions, which is related to the infiltration and metastasis of tumor cells." (PMID 38493179, 2024). "The strong association between low CLDN3 expression and unfavorable prognostic tumor features may suggest a clinically useful role of CLDN3 expression measurement in ccRCC." (PMID 39658782, 2024). "Furthermore, we found that the gene encoding the tight junction protein 3 (Claudin3/CLDN3) is specifically expressed in tumor stem cells." (PMID 38534739, 2024). "Altered CLDN3 expression has been linked to tumor progression in multiple tumor types." (PMID 39658782, 2024). "The result showed that loss of claudin-3 led to increased lymphangiogenesis at primary tumor sites." (PMID 36261482, 2022). "Numerous studies demonstrated that in vitro and in vivo treatment with recombinant CPE exerted cytotoxic effects via pore formation (oncoleaking) on high Cldn3/4 expressing pancreatic, ovarian and breast cancer cells, which was associated with tumor reduction or elimination." (PMID 34503203, 2021). "These conjugates exhibit potent binding and effectively inhibit the growth of tumor cells with high levels of both EpCAM and CLDN3, indicating their anti-tumor efficacy." (PMID 40057807, 2025). "We further detected the protein expression levels of EPCAM and CLDN3 on these tumor cells by FACS, and the results were consistent with mRNA expression." (PMID 40057807, 2025). "Pharmacokinetic profiles of EpCAM X CLDN3 BsADC 3 and total antibody in non-tumor bearing mice were evaluated after single intravenous administration of BsADC 3 and the IgG-ADC at doses of 10 mg/kg." (PMID 40057807, 2025). "Our BsADC molecules have strong binding activities to tumor cells with high EpCAM and CLDN3 expression, and also exhibited stronger ADCC, ADCP, and CDC effects than their parental bivalent antibodies on OVCAR-3 cells." (PMID 40057807, 2025).
tumor (continued). "In the NCI-H1781 and MCF7 models with high expression of both EpCAM and CLDN3, BsADC 3 demonstrated more potent anti-tumor activity than the EpCAM parental monoclonal ADC." (PMID 40057807, 2025). "This novel BsADC demonstrated significant cytotoxicity against various tumor cell lines expressing EpCAM and CLDN3 both in vitro and in vivo." (PMID 40057807, 2025). "Here, we generated a BsADC targeting EpCAM and CLDN3 to deliver potent toxin payload more precisely to the tumors and mitigate on-target off-tumor toxicity." (PMID 40057807, 2025). "Mechanisms that were suggested to explain a tumor promoting role of CLDN3 in cancer include a regulatory impact on cancer stemness and increased chemoresistance." (PMID 39658782, 2024). "Alternatively, it cannot be excluded that reduced CLDN3 expression in tumors derived from CLDN3 expressing normal cells merely reflects tumor cell dedifferentiation which always parallels cancer progression." (PMID 39658782, 2024). "The results of our successful analysis of 14,966 tumors from 133 different tumor categories provide a comprehensive overview of CLDN3 expression in cancer." (PMID 39658782, 2024). "In conclusion, our data demonstrate significant levels of CLDN3 expression in many different tumor entities and identify reduced CLDN3 expression as a potential prognostic marker in RCC." (PMID 39658782, 2024). "Our data demonstrate significant levels of CLDN3 expression in many different tumor entities, and show that both increased and decreased levels of CLDN3 can occur during tumor progression in a cancer type dependent manner." (PMID 39658782, 2024). "A link between reduced CLDN3 expression and poor patient outcome or unfavorable tumor characteristics was previously also found in other cancer types." (PMID 39658782, 2024). "CLDN3 staining was found in 96 of 133 tumor categories, 80 of which contained at least one strongly positive case." (PMID 39658782, 2024). "Knockdown of CLDN3 or CLDN4 in tumor cell lines results in reduced tight junction formation and increased invasiveness." (PMID 38326579, 2024). "At least an occasional weak CLDN3 positivity was detected in 96 of 133 tumor categories and 80 categories included at least one case with strong CLDN3 positivity." (PMID 39658782, 2024). "For example, claudin 3 is a tumor suppressor, as demonstrated by tumor growth in intestinal-claudin-3-knockout mice." (PMID 37239907, 2023). "Nevertheless, tumour-specific drug delivery will be required since claudin 3 and 4 are highly expressed in normal gut, lung, and kidney, all of which are indispensable for survival." (PMID 36714681, 2023). "By contrast, other studies have found that CLDN3 silencing reduces cell proliferation and tumor growth." (PMID 36614243, 2023). "Most studies focus on the expression of claudin-3 on tumor epithelial cells affect tumor metastasis." (PMID 36261482, 2022). "All patients were analyzed concerning the expression of claudin-3 in tumor and control tissues since an immunohistochemical study presented claudin-3 in OSCC and in the healthy oral epithelium." (PMID 36232536, 2022). "Our results suggest that the expression of claudin-3 protein in the tumor microenvironment is closely related to lymphangiogenesis by affecting LECs activity." (PMID 36261482, 2022). "Immunohistochemistry (IHC) results indicated that claudin-3 was expressed on lymphatic vessels in B16F10 tumor tissues." (PMID 36261482, 2022). "Previous studies have shown that the expression of claudin-3 on epithelial cells contributes to the tumor progression by affecting certain signaling pathways." (PMID 36261482, 2022). "Claudin-3(CLDN3) has an important cell-to-cell tight-junction function, while tumor development and metastasis are thought to involve with the loss of tight-junction function." (PMID 36010914, 2022). "In the present study, we built a B16F10 metastasis tumor model using claudin-3-null (claudin-3−/−) mice." (PMID 36261482, 2022).
tumor (continued). "This subtype is characterized by a low expression of claudin 3&4&7, and these claudin proteins are crucial for endothelial cells to form a substantial barrier between tumor tissue and blood vessel." (PMID 35359417, 2022). "Quantification and statistical analysis by Inform software confirmed that the LYVE1+ area was increased in tumor sites of claudin-3−/− mice indicating the presence of more lymphatic vessels existed." (PMID 36261482, 2022). "We then detected lymphatic vessels in tumor site and found increased lymphangiogenesis in claudin-3−/− mice compared with the control." (PMID 36261482, 2022). "The imaging of C-CPE binding to the canine tumor cell lines proved that the protein can specifically target CLDN-3, -4, and -7, demonstrating that the functionalization did not alter the binding capacity to CLDN." (PMID 34830170, 2021). "Many studies have described the highly specific interaction of CPE and Cldn3/4, which is essential for selective tumor cell killing." (PMID 34503203, 2021). "In high Cldn3/4 expressing Capan-1/eGFP-Luc CDX tumor bearing mice jet-injection optCPE gene transfer also led to significant reduction of tumor viability reflected by the reduced tumor bioluminescence signals in vivo and ex vivo." (PMID 34503203, 2021). "Our single-cell analysis revealed that BRAF V600E mutation tumor epithelial cells highly expressed TACSTD2 and CLDN3, which were then validated in TCGA data." (PMID 34805166, 2021). "Next, we determined CPE gene transfer mediated selective tumor cell killing in Cldn3/4 positive Capan-1, PA-TU-8902, AsPc-1, MIA PaCa-2, BxPC-3 and HUP-T3 cells as well as the negative control cell line SK -MEL-5 and the positive control line HT-29." (PMID 34503203, 2021). "For example, silencing Cldn3 using small interfering RNA (siRNA) resulted in suppression of ovarian xenograft tumor growth and metastasis." (PMID 35006480, 2021). "In particular, claudin-4 and claudin-7 transcript levels were increased by over 2-fold in normal fallopian tubes compared to tumor samples (both p < 0.001), whereas claudin-3 showed a 1.18-fold increase in fallopian tubes compared to HGSOCs (p = 0.305)." (PMID 32850397, 2020). "The depletion of claudin-3 was able to combat the formation of spheres and tumor formation as well as increased sensitivity to cisplatin." (PMID 31861759, 2019). "The h4G3 conjugated to a fluorescent dye showed a lower distribution in normal tissues than in the tumor site in mice bearing xenograft tumors despite its ability to recognize mouse CLDN3." (PMID 31905631, 2019). "Both CPE- and C-CPE-based cancer therapies have shown promising anti-tumor efficacy and provide proof of concept for CLDN3-targeted therapy." (PMID 31905631, 2019). "The biodistribution of h4G3 was analyzed by intravenous injection of fluorescence-conjugated h4G3 which showed that it localized to the tumor site in xenograft mice bearing CLDN3-expressing tumors." (PMID 31905631, 2019). "In a recent report, we showed that C-CPE -functionalized AuNPs in combination with GNOME-LP efficiently killed tumor cells expressing CLDN-3, -4, and -7, documented by the uptake of membrane impermeable of molecule such as propidium iodide." (PMID 31480250, 2019). "In an univariate analysis of clinicopathological factors associated with BRCA1-mutated BC versus the WT subtype, tumor grade, ER, PR, and expression of CK5, CK14, and CLDN3 were found to be independent parameters." (PMID 31307407, 2019). "Several studies have shown that downregulation of CLDN3 inhibits tumour growth in vivo and in vitro by promoting tumour cell apoptosis, inhibiting cell proliferation and reducing angiogenesis." (PMID 29966369, 2018). "The elevated expression of claudin-3, -4 and -7 in tumor development is particularly interesting since they are natural receptors for the CPE21–25." (PMID 30297847, 2018).
tumor (continued). "The use of C. perfringens enterotoxin (CPE) to target tumor cells raised after it was observed that the development of many tumor types correlated with a dysregulated expression of claudin-3 -4 or -715–17." (PMID 30297847, 2018). "Using qPCR and immunocytochemistry, we identified the human Caco-2, MCF-7 and OE-33 as well as the canine TiHoDMglCarc1305 as tumor cells expressing claudin-3, -4 and -7." (PMID 30297847, 2018). "To clarify the correlation between c-kit and claudin-3, we collected 12 tumor samples from CRC patients and matched adjacent normal tissues." (PMID 28383479, 2017). "These tumours also expressed Claudin 3 and E-Cadherin, but contained fewer K5+ cells (Type 2 tumours)." (PMID 28194015, 2017). "We confirmed tumor-specific overexpression for three genes (CDH11, ICAM1 and CLDN3) using qRT-PCR, and demonstrated protein localization specific to the cell surface of tumor cells by IHC." (PMID 27363029, 2016). "Based on the score of staining, the average protein level of CLDN3 was significantly lower in HCC tumor tissues than that in adjacent normal tissues (1.2 vs. 2.4; P<0.0001)." (PMID 25277196, 2014). "Our data indicate an inverse association between Twist and E-cadherin and Twist and CLDN3 and CLDN4, further attesting to its role in EMT and tumor progression." (PMID 23805314, 2013). "Some claudins also have been shown to have a prognostic role in particular tumor types, for example, claudin-3/-4 has a prognostic role in ovarian cancer, claudin-1 in colon cancer, claudin-10 in hepatocellular carcinoma and claudin-18 in gastric cancer." (PMID 23685873, 2013). "Cytotoxicity of up to 100% was observed 72 h after gene transfer and was restricted to claudin-3 and -4 expressing tumor lines." (PMID 23685873, 2013). "In this study, immunohistochemical analysis was performed for claudin-3 and -4 expression in both the distal fallopian tube and tumor in six cases of serous ovarian cancer." (PMID 23685873, 2013). "Intra-tumoral gene transfer of CPE-expressing vectors can be employed for selective suicide gene therapy of claudin-3 and -4 positive tumors and was found to effect a more rapid and effective tumor cell killing in vitro and in vivo." (PMID 23685873, 2013). "On the other hand, CLDN3,4, and 7 were highly expressed in most normal epithelial cells as well as their corresponding neoplasias." (PMID 16836752, 2006). "The cytotoxic effect was dose dependent and was positively correlated to the levels of either claudin-3 or claudin-4 expression as tested by RT–PCR in tumor samples." (PMID 15785748, 2005). "In these cases the results of immunohistochemistry and real-time PCR appeared to correlate; specifically, CLDN1 appeared to be downregulated in tumours as compared with normal breast, whereas CLDN3 was expressed at similar levels in tumours and normal breast." (PMID 15743508, 2005). "Our observations suggest that, in breast tissue, CLDN3 expression is similar in tumours and surrounding normal tissue, as demonstrated by immunohistochemistry and real-time PCR." (PMID 15743508, 2005). "Meanwhile, we also detected the expression of EpCAM and CLDN3 in 16 tumor cell lines by RT-PCR." (PMID 40057807, 2025). "However, in the HCT116 and SNU-5 models with high expression of EpCAM but low expression of CLDN3, the anti-tumor activity of BsADC 3 was close to EpCAM monovalent ADC, significantly lower than that of the EpCAM parental monoclonal ADC." (PMID 40057807, 2025). "CLDN3 exhibits tumor-suppressive functions in lung squamous cell carcinoma (SqCC)." (PMID 40687428, 2025). "Importantly, cKM3907 (fused to a IgG1 Fc domain) also had CDC activity and prevented measurable tumor formation of CLDN3 or CLDN4 transfected Chinese hamster ovary (CHO) when injected into SCID mice." (PMID 38371623, 2024).